B3GNT4 (UDP-GlcNAc:betaGal beta-1,3-N-acetylglucosaminyltransferase 4)
Description:
Beta-1,3-N-acetylglucosaminyltransferase involved in the synthesis of poly-N-acetyllactosamine. Has activity for type 2 oligosaccharides.
Synonyms: Beta3Gn-T4; B3GN-T4
Tractability: Antibody: UniProt predicts a signal peptide or a membrane-spanning region.
Target class: Enzyme; Transferase
Gene: Protein-coding gene on chromosome 12 (122,203,681 to 122,208,952, forward strand). Ensembl gene ENSG00000176383.
Subcellular location: Golgi apparatus membrane
Subcellular location (Human Protein Atlas): Mitochondria; Nucleoli
Pathways (Reactome):
Metabolism: Keratan sulfate biosynthesis
Metabolism of proteins: O-linked glycosylation of mucins
Gene Ontology:
Molecular function: N-acetyllactosaminide beta-1,3-N-acetylglucosaminyltransferase activity; acetylglucosaminyltransferase activity; hexosyltransferase activity
Biological process: poly-N-acetyllactosamine biosynthetic process; keratan sulfate proteoglycan biosynthetic process; glycoprotein biosynthetic process
Cellular component: Golgi membrane; membrane
Genetic constraint (gnomAD): Loss-of-function variants: 3 observed, 2.25 expected, observed/expected ratio (o/e) 1.34, 90% interval 0.53 to 1.92. That is too few expected variants to judge how well the gene tolerates losing a copy. Missense variants: 698 observed, 504.69 expected, observed/expected ratio (o/e) 1.38, 90% interval 1.3 to 1.47. Synonymous variants: 272 observed, 211.11 expected, observed/expected ratio (o/e) 1.29, 90% interval 1.17 to 1.42.
Homologues: Orthologues: chimpanzee B3GNT4 (98% identical), macaque B3GNT4 (90% identical), dog B3GNT4 (84% identical), pig B3GNT4 (78% identical), rat B3gnt4 (74% identical), mouse B3gnt4 (73% identical), tropical clawed frog b3gnt4 (53% identical), Drosophila melanogaster brn (26% identical), Caenorhabditis elegans bre-5 (19% identical), Caenorhabditis elegans F21C10.3 (10% identical), Caenorhabditis elegans B0024.3 (8% identical). Paralogues in human: B3GNT7 (40% identical), B3GNT9 (39% identical), B3GNT6 (37% identical), B3GNT3 (36% identical), B3GNT2 (36% identical), B3GNT8 (31% identical), B3GNT5 (27% identical), B3GALT4 (26% identical), B3GALT2 (24% identical), B3GALT9 (24% identical), B3GALNT1 (23% identical), B3GALT5 (23% identical), and 3 more.
Diseases named in the same sentence as B3GNT4 in open-access papers:
B3GNT4 is named in the same sentence as 2 diseases in open-access papers, as found by Europe PMC text mining. Sharing a sentence is not in itself a finding about the gene and the disease. The quoted sentences say what the papers report.
cancer (3 papers, 2022 to 2025). A tumor composed of atypical neoplastic, often pleomorphic cells that invade other tissues. "Namely, increased B3GNT4 expression was associated with subclonal expansion in at least seven tumor types, while GALNT16 and GALNT17 levels appeared mostly associated with a decrease in intra-tumor heterogeneity across five cancers." (PMID 36009354, 2022). "As for elongation, B3GNT3, B3GNT4, and GCNT3 were highly expressed in both cancer types (LUAD and LUSC)." (PMID 40718829, 2025).
tumor (2 papers, 2022 to 2025). "Glycosyltransferases—including B3GAT3, B3GNT4, and B4GALT2—play distinct yet interconnected roles in glycan biosynthesis, which can influence tumor biology." (PMID 40963867, 2025).